MYH15 (myosin heavy chain 15)
Description:
Muscle contraction.
Synonyms: KIAA1000
Tractability: PROTAC: ubiquitination databases record sites on it.
Gene: Protein-coding gene on chromosome 3 (108,380,368 to 108,529,322, reverse strand). Ensembl gene ENSG00000144821.
Subcellular location: Cytoplasm, myofibril
Subcellular location (Human Protein Atlas): Cytosol; Vesicles
Gene Ontology:
Molecular function: actin filament binding; microfilament motor activity; ATP binding; cytoskeletal motor activity
Biological process: extraocular skeletal muscle development; muscle system process
Cellular component: cytoplasm; myosin filament; myosin II complex; myofibril; myosin complex
Genetic constraint (gnomAD): Loss-of-function variants: 191 observed, 211.13 expected, observed/expected ratio (o/e) 0.9, 90% interval 0.8 to 1.02. The upper end of that interval is the gene's LOEUF score, 1.02, which puts it in group 4 of 6, group 1 being the genes least tolerant of losing a copy. Missense variants: 2,020 observed, 2,125.9 expected, observed/expected ratio (o/e) 0.95, 90% interval 0.92 to 0.99. Synonymous variants: 720 observed, 763.2 expected, observed/expected ratio (o/e) 0.94, 90% interval 0.89 to 1.
Homologues: Orthologues: chimpanzee MYH15 (99% identical), macaque MYH15 (96% identical), pig MYH15 (82% identical), dog MYH15 (80% identical), guinea pig MYH15 (78% identical), mouse Myh15 (76% identical), rat Myh15 (75% identical), tropical clawed frog myh7b (65% identical), zebrafish myh7ba (63% identical). Paralogues in human: MYH6 (63% identical), MYH7 (62% identical), MYH7B (61% identical), MYH13 (60% identical), MYH2 (60% identical), MYH3 (60% identical), MYH4 (60% identical), MYH8 (60% identical), MYH1 (60% identical), MYH9 (38% identical), MYH10 (38% identical), MYH11 (38% identical), and 32 more.
Diseases named in the same sentence as MYH15 in open-access papers:
MYH15 is named in the same sentence as 19 diseases in open-access papers, as found by Europe PMC text mining. Sharing a sentence is not in itself a finding about the gene and the disease. The quoted sentences say what the papers report.
ischemic stroke (2 papers, 2019). A stroke disorder caused by obstruction of blood flow to the brain, due to thrombotic (local blood clot formation) or embolic (due to a blood clot or other material traveling from another site) event. "Variants in MYH15 were reported to be associated with higher risk for non-cardioembolic stroke and ischemic stroke." (PMID 30967136, 2019).
pulmonary hypertension (2 papers, 2019). Increased pressure within the pulmonary circulation due to lung or heart disorder. "In addition, a SNP in MYH15 has been linked to bovine pulmonary hypertension, supporting a role for MYH15 in the pulmonary system." (PMID 30836986, 2019). "Interestingly, it is associated with bovine pulmonary hypertension related to high altitude, suggesting that MYH15 could be involved in the response to hypoxic conditions." (PMID 31624339, 2019).
airway hyperresponsiveness (1 paper, 2019). "As airway hyperresponsiveness is one of the representative pathophysiological mechanisms of asthma, we hypothesized that polymorphisms of MYH15 would be associated with asthma and this is what we demonstrated in the Chinese Han in the present study." (PMID 30906771, 2019).
asthma (1 paper, 2019). "This study was the first attempt to investigate the association between MYH15 and asthma in the Chinese population and to identify the functional SNPs." (PMID 30906771, 2019). "The aim of this study was to perform the first investigation of MYH15 polymorphisms in relation to asthma susceptibility." (PMID 30906771, 2019). "This is the first study to report the association of MYH15 gene polymorphisms with asthma." (PMID 30906771, 2019). "Polymorphisms of rs9288876, rs7635009, and rs1454197 altered transcriptional regulation of MYH15 and may be functional variants conferring susceptibility to asthma." (PMID 30906771, 2019). "The MYH15 rs9288876 allele A, rs7635009 allele G, and rs1454197 allele G may reduce the risk of asthma." (PMID 30906771, 2019). "In this work, we are the first to demonstrate that MYH15 polymorphisms may be associated with asthma in the Chinese Han population." (PMID 30906771, 2019). "Therefore, the aim of this study was to investigate the association of polymorphisms of MYH15 with asthma susceptibility in the Chinese Han population." (PMID 30906771, 2019). "In conclusion, MYH15 gene polymorphisms may be associated with asthma in the Chinese Han population." (PMID 30906771, 2019). "Although the results after the multiple testing correction were negative, it is still possible that MYH15 variants are related to asthma in the Chinese Han population in light of the positive functional analysis." (PMID 30906771, 2019). "However, to date there have been no studies of the association between MYH15 polymorphisms and asthma." (PMID 30906771, 2019).
chronic obstructive pulmonary disease (1 paper, 2019). A chronic and progressive lung disorder characterized by the loss of elasticity of the bronchial tree and the air sacs, destruction of the air sacs wall, thickening of the bronchial wall, and mucous accumulation in the bronchial tree. "Recently, MYH15 polymorphisms were associated with airway responsiveness (p=5.41x10−8) and the protein was shown to be expressed in the airway epithelium and alveolar macrophages of patients with chronic obstructive pulmonary disease (COPD)." (PMID 30906771, 2019).
colorectal cancer (1 paper, 2019). A primary or metastatic malignant neoplasm that affects the colon or rectum. "However, MYH15 proteins are expressed in glioma, urothelial and colorectal cancers (HPA data)." (PMID 30967136, 2019).
frontotemporal lobar degeneration (1 paper, 2019). "In addition, proteome studies revealed deferential expression of MYH15 in early onset dementia, an atypical frontotemporal lobar degeneration (aFTLD)." (PMID 30967136, 2019).
lung disease (1 paper, 2019). "Thus, NSCLC cells respond to TGFβ-stimulation with upregulation of several cancer type unspecific (VIM, MYLK, MYL9, TPM1) but also more lung disease specific (MYH15) proteins." (PMID 31113982, 2019).
cancer (4 papers, 2019 to 2025). A tumor composed of atypical neoplastic, often pleomorphic cells that invade other tissues. "Cytoskeletal alterations are a hallmark of cancer, particularly in metastasis, and MYH15 dysregulation may facilitate AML progression." (PMID 40506993, 2025). "The MYH15 (Myosin Heavy Chain 15) gene, primarily involved in muscle physiology, has emerging implications in cancer biology." (PMID 40506993, 2025). "Among them, five genes (FGG, MYH15, STARD4, SYTL4, and TMEM267) were first associated with cancer procession, while the other three (KRT81, KRT6A, and KRT13) have previously been confirmed to be related to cancer metastasis and migration." (PMID 37817112, 2023). "MYH15 myosin was selected in this study for a closer analysis because of potential involvement of non-muscle class II myosins in tumor progression, cancer cell invasion, metastasis and EMT50." (PMID 31113982, 2019).
tumor (2 papers, 2019). "However, further studies are required to elucidate the mechanisms by which MYH3 and MYH15 can promote tumor pathogenesis." (PMID 30967136, 2019).
heart disease (1 paper, 2010). "SNP variants in MYH15 are associated with elevated risk for heart disease." (PMID 20226094, 2010).
infection (1 paper, 2022). The state of being infected such as from the introduction of a foreign agent such as serum, vaccine, antigenic substance or organism. "Angptl4, which contributes to the anti-inflammatory response and Myh15, were downregulated in 5-ASKH infection." (PMID 36190414, 2022).
MYH15 also shares sentences with these, for which no sentence is quoted: deafness (2 papers); bacterial infection (1); colon cancer (1); coronary heart disease (1); glioma (1); respiratory diseases (1); yang deficiency (1).